MCM4 (minichromosome maintenance complex component 4)
Diseases named in the same sentence as MCM4 in open-access papers (continued):
Sharing a sentence is not in itself a finding about the gene and the disease.
ureter (1 paper, 2023). "MCM4-positive UTUC cases were associated with ages > 70 years (P = 0.0410), ureter UC (P = 0.0309), nodular/flat morphology (P = 0.0086), high tumor grade (P < 0.0001) and high pathological T stage (P < 0.0001)." (PMID 37737200, 2023).
urothelial carcinoma (1 paper, 2023). A malignant neoplasm derived from the transitional epithelium of the urinary tract (urinary bladder, ureter, urethra, or renal pelvis). "However, the clinicopathological significance of MCM4 in urothelial carcinoma (UC) has not been investigated." (PMID 37737200, 2023).
uterine carcinosarcoma (1 paper, 2025). A usually aggressive malignant neoplasm arising from the uterine corpus and less often the cervix. "The overall alteration frequency of MCM4 was 4.0%, with the highest occurrence observed in uterine carcinosarcoma (~16%)." (PMID 40959096, 2025).
cancer (70 papers, 2008 to 2025). A tumor composed of atypical neoplastic, often pleomorphic cells that invade other tissues. "Our investigation revealed significant associations between MCM4 expression levels and various genetic alterations in specific cancer types." (PMID 38499612, 2024). "Only in KICH, KIRP, LIHC, LUAD, OV, and UCS were there significant associations between MCM4 expression level and cancer stage." (PMID 38499612, 2024). "We found that mutations in MCM4 were frequent in cancer samples, and that phosphorylation levels of MCM4 were also elevated in 8 cancer types." (PMID 38499612, 2024). "We also investigated the association of MCM4 expression with immune infiltrates in different cancers." (PMID 38499612, 2024). "Strong diagnostic potential with AUC values above 0.7 was found in 19 types of cancer when utilizing MCM4 as a diagnostic biomarker." (PMID 38499612, 2024). "The expression of MCM4 has been found to be associated with molecular subtypes in eleven different types of cancer and 14 types of immune classifications." (PMID 38499612, 2024). "Our aim was to investigate the frequency of somatic mutations in the MCM4 in various categories of cancer by examining a cohort of 32 tumor tissue samples." (PMID 38499612, 2024). "Research has found that MCM4 undergoes mutations in numerous cancer types, with the highest mutation rate observed in UCS, exceeding 15%." (PMID 38499612, 2024). "This research aims to comprehensively evaluate the expression patterns, functional implications, and diagnostic potential of MCM4 in various cancer types." (PMID 38499612, 2024). "We also evaluated the association between MCM4 expression and representative cancer-related molecules." (PMID 37737200, 2023). "The increase in genomic instability seen with a hypomorphic MCM4 allele led to an increased cancer rate in the mouse." (PMID 33477564, 2021). "A dominant allele of mouse Mcm4 (D573H) enhanced genome instability leading to increased incidence of cancer development." (PMID 29651420, 2018). "One mutation that exhibits severely defective hexamerization and ssDNA-binding is at a conserved phenylalanine that aligns with the mouse Mcm4(Chaos3) mutation associated with chromosomal instability, cancer, and decreased intersubunit association." (PMID 26365238, 2015). "The dominant inheritance of the cancer phenotype observed in Sdl contrasts to previous studies of mice harboring Mcm2 (Mcm2IRES-CreERT2) or Mcm4 (Mcm4chaos3) hypomorphic alleles in which tumors were only observed in the homozygous state." (PMID 23133403, 2012). "In genomic analysis, we have observed multiple gene site mutations in MCM4 across pan-cancer." (PMID 40959096, 2025). "Existing studies have reported that exceptional phosphorylation and mutation of MCM4 have implications in the dysfunction of a variety of biological processes and may be contributors to cancer development." (PMID 38499612, 2024). "On the other hand, mutations in the MCM4 gene are also associated with the occurrence of cancer." (PMID 38499612, 2024). "Furthermore, we employed the “Pathological Stage Plot” module of GEPIA2 to assess the association between MCM4 expression and cancer pathological stages across various cancer types." (PMID 38499612, 2024). "Bioinformatic tools were then introduced to explore the expression profiles, genetic alterations, phosphorylation states, patterns of immune cell infiltration, immune subtypes, disease prognosis, as well as the diagnostic potential of MCM4 and its responsiveness to drugs in a range of cancers." (PMID 38499612, 2024). "Some studies have indicated the presence of MCM4 gene mutations in certain cancers, which may affect the structure and function of the MCM complex, thereby influencing the normal progression of DNA replication." (PMID 38499612, 2024). "Third, our study did not delve into the molecular mechanism underlying the role of MCM4 in cancers." (PMID 38499612, 2024).
cancer (continued). "Increased MCM4 expression was significantly associated with unfavorable OS prognosis in several cancer types, including ACC (P = 0.0035), LGG (P = 0.00085), LUAD (P = 0.00092), MESO (P = 0.0031), PAAD (P = 0.013), SARK (P = 0.021), SKCM (P = 0.028), and UVM (P = 0.01)." (PMID 38499612, 2024). "However, we also found that MCM4 expression was inversely associated with the degree of TGCT’s infiltration by cancer-associated fibroblasts." (PMID 38499612, 2024). "It is unclear if MCM4 pathogenic variants lead to cancer in humans as well." (PMID 33477564, 2021). "GATA2 and MCM4 mutations are found in NKD patients with cancer." (PMID 31379882, 2019). "Our results indicated a positive correlation between MCM4 expression and the extent of infiltration of cancer-associated fibroblasts in various forms of cancer, suggesting that MCM4 may play a key role in promoting fibroblast recruitment into the tumor microenvironment." (PMID 38499612, 2024). "We conducted pan-cancer expression analysis and found that MCM4 expression was markedly elevated in most cancer types." (PMID 40959096, 2025). "To evaluate the prognostic significance of MCM4 across pan-cancer, we performed univariate Cox regression analysis." (PMID 40959096, 2025). "In cancer, MCM4 is frequently overexpressed, contributing to genomic instability and tumor progression." (PMID 40564876, 2025). "To assess the impact of MCM4 on tumor stemness across pan-cancer, we conducted a Spearman correlation analysis, revealing an extensive positive correlation between MCM4 expression and stemness." (PMID 40959096, 2025). "While significant research is still needed, targeting MCM4 remains a promising avenue for developing novel cancer therapies." (PMID 40959096, 2025). "Our findings were further supported by the Depmap database's cancer dependency analysis of MCM4, which used RNA interference and CRISPR technology to show strong essentiality of MCM4 in a variety of cancer cell lines." (PMID 38499612, 2024). "Overall, our study provides new insights into the relationship between MCM4 expression and immune infiltration in various cancer types." (PMID 38499612, 2024). "The employment of CRISPR for MCM4 knockdown and RNAi for interference with its expression elucidated a notable suppression of tumor cell growth in cancer cell lines across various cancer types." (PMID 38499612, 2024). "Our analysis unveiled a significant upregulation of MCM4 protein expression in diverse cancer types when compared to normal tissues." (PMID 38499612, 2024). "Increasing evidence has confirmed the overexpression of MCM4 in several cancers like hepatocellular carcinoma, soft-tissue sarcoma, esophageal cancer, glioma and uterine corpus endometrial carcinoma." (PMID 38499612, 2024). "Eleven types of cancer were found to have molecular subtypes that are related to the expression of MCM4." (PMID 38499612, 2024). "This study aims to bridge this knowledge gap by presenting a thorough pan-cancer analysis of MCM4, shedding light on its functional implications and potential clinical applications." (PMID 38499612, 2024). "In miscellaneous TCGA cancers, the correlation between MCM4 expression and molecular and immunological subtypes was found to be significant." (PMID 38499612, 2024). "Our findings provide insight into the potential role of MCM4 in modulating several cellular processes that contribute to cancer development and progression." (PMID 38499612, 2024). "We finally analyzed the relationship between MCM4 expression and drug sensitivity in miscellaneous cancer types." (PMID 38499612, 2024). "Our research demonstrates that MCM4 is closely associated with the oncogenesis, prognosis and diagnosis of various tumors and proposes that MCM4 may function as a potential biomarker in pan-cancer, providing a deeper understanding of its potential role in cancer development and treatment." (PMID 38499612, 2024).
cancer (continued). "Future research should continue to explore the functional relationships between MCM4 and other genes in the context of cancer, with the goal of identifying novel mechanisms of tumorigenesis." (PMID 38499612, 2024). "Our findings demonstrated a noteworthy increase in MCM4 expression across 22 various cancer types, in contrast to normal tissue." (PMID 38499612, 2024). "MCM4, an essential member of the minichromosomal maintenance protein family, has been shown to play a crucial role in numerous human cancers, particularly in NSCLC." (PMID 38163864, 2024). "In conclusion, our study provides evidence that MCM4 plays a crucial role in modulating various cellular processes that contribute to cancer development and progression." (PMID 38499612, 2024). "Recently, there has been a growing interest in investigating the significance of MCM4 in different types of cancer." (PMID 38499612, 2024). "Among representative cancer-related molecules, MCM4 had an independent predictive value for progression-free survival and high-grade UC." (PMID 37737200, 2023). "We used functional experiments including cell proliferation, invasion, migration assays, and clone formation assay to validate the oncogenic effect of novel cancer genes MCM4." (PMID 37491836, 2023). "MCM4 mutation affected its interaction with MCM7 to induce the destabilization of MCM4/6/7 complex and contributed to cancer cell development." (PMID 37491836, 2023). "The mutation frequencies of MCM4 and CXCL6 were 0.69% and 0.34% in GBM, which was too low to be identified by the methods based on cancer population." (PMID 37491836, 2023). "By referring to related literatures and databases, E2F1, GLI1, CDK3, and Mcm4, as candidate target genes, were found to be closely related to the occurrence of cancers, which was very helpful to clarify the mechanism of EZH2 in PC." (PMID 37198697, 2023). "In the personalized driver gene‐hallmark network, we found that the major contributions of MCM4 and CXCL6 were to different cancer hallmarks." (PMID 37491836, 2023). "Mutations in MCM4 disrupt the functions of MCM2–7, resulting in genomic instability and cancer progression." (PMID 35360518, 2022). "Based on The Cancer Genome Atlas (TCGA) and Genotype-Tissue Expression (GTEx) databases, the expression levels of MCM4 in pan-cancer were first explored." (PMID 35719366, 2022). "This suggested that the pro-oncogenic mechanism of MCM4 in LUAD was similar to that of other pan-cancer mechanisms." (PMID 36291859, 2022). "The levels of MCM4 in cancer were markedly upregulated in 67 datasets and downregulated in nine datasets compared to that in normal tissues." (PMID 34178669, 2021). "MCM4 which was also at a central position in the network is essential for DNA replication and has already been described in other human cancer entities." (PMID 27172797, 2016). "One explanation for these outcomes is that the Chaos3 mutation impairs MCM4 biochemically in a manner leading to elevated replication fork defects, and that these defects lead to the GIN and cancer phenotypes." (PMID 20838603, 2010). "Celastrol treatment induces the downregulation of MCM4 in cancer cells." (PMID 39901144, 2025). "Previous study has showed that MCM4 functions as a cancer-promoting gene in UCEC." (PMID 39901144, 2025). "Pan-cancer analysis revealed a significant positive association between SRF and MCM4." (PMID 40959096, 2025). "We previously reported MCM4 as a molecule associated with cancer stem cells; however, its role in PDAC has not been reported." (PMID 40293517, 2025). "Our research also establishes the foundation for MCM4 as a pan-cancer biomarker." (PMID 40959096, 2025).
cancer (continued). "Similarly, MCM proteins, which are essential for DNA replication licensing and serve as emerging proliferation markers, were significantly associated with C1GALT1 expression—most notably MCM4 and MCM6, which were consistently correlated across cancers." (PMID 40548474, 2025). "Single-cell analysis also revealed that MCM4-expressing cells were located upstream of the trajectory, with a cluster showing a correlation with KIFC1, which has been reported to be associated with cancer stemness." (PMID 40293517, 2025). "Given the established roles of MMPs in extracellular matrix degradation and cancer cell invasion, these correlations reinforce the notion that MCM4 may promote LUAD progression through enhancing metastatic and invasive potential." (PMID 40564876, 2025). "We also evaluated the effectiveness of MCM4 in predicting the diagnosis of cancer patients." (PMID 38499612, 2024). "Furthermore, we conducted a comprehensive analysis of the relationship between MCM4 expression and drug sensitivity across various cancer types using drug sensitivity genomics." (PMID 38499612, 2024). "However, the majority of studies investigating the role of MCM4 in cancer have been confined to specific cancer types, thus creating a knowledge gap regarding its involvement across various cancers." (PMID 38499612, 2024). "Moreover, the predicted values of MCM4 spanned a range of 0.788 to 0.989 across the other 15 types of cancer." (PMID 38499612, 2024). "Thus, we investigated the molecular structure and gene alterations of MCM4 to further explore the link between MCM4 and cancer." (PMID 38499612, 2024). "We aimed to evaluate the prognostic implications of MCM4 expression in various cancer types." (PMID 38499612, 2024). "Future studies should continue to explore the functional implications of MCM4 expression in the context of cancer development and progression, with a focus on elucidating the molecular mechanisms underlying its effects on immune cell infiltration and tumor-immune cell interactions." (PMID 38499612, 2024). "Finally, we explored the potential of MCM4 as a cancer biomarker and its correlation with poor prognosis in various cancers." (PMID 38499612, 2024). "In conclusion, this comprehensive study addresses a significant research gap by investigating the role of MCM4 in diverse cancer types and confirms that it may have translational implications for the diagnosis of cancer and strategies for its treatment." (PMID 38499612, 2024). "Conversely, a negative correlation was observed between MCM4 expression and cancer-associated fibroblast infiltration in TGCT." (PMID 38499612, 2024). "We also detected a strong correlation between MCM4 expression and cancer progression." (PMID 38499612, 2024). "Specifically, the CRISPR study demonstrated a significant effect of MCM4 on tumor cells, evident in both the overall analysis and individual cell line assessments across all cancer types, with all gene effects registering below 0 and a mean effect skewed leftward of -1." (PMID 38499612, 2024). "Consequently, we investigated the correlation between MCM4 expression and the level of immune infiltration in various immune cells across TCGA cancers." (PMID 38499612, 2024). "In addition, MCM4 was an independent prognostic marker for PFS compared to representative cancer-related markers." (PMID 37737200, 2023). "Several studies have shown that the expression of MCM4 in cancer is regulated by many factors." (PMID 37737200, 2023). "Cancers arising in different anatomic sites are also associated with minichromosome maintenance complex component 2 (MCM2), MCM4, and minichromosome maintenance complex component 6 (MCM6) overexpression, but there is not much information about the role of MCM4 in PC." (PMID 36329790, 2023).